ANXA2 (annexin A2)
Diseases named in the same sentence as ANXA2 in open-access papers (continued):
Sharing a sentence is not in itself a finding about the gene and the disease.
tumor (continued). "It is surprising to note that annexin A2 was been previously reported to be upregulated in various tumor types with a role in cell migration, invasion and adhesion, but is downregulated in PC3-ML2 compared to PC3-N2 in our current study." (PMID 23717685, 2013). "Our findings suggest the reduced tumor burden and metastatic spread in the annexin A2 antibody treatment group is a result of reduced cell survival." (PMID 23945256, 2013). "We showed that the growth of tumours initiated by the subcutaneous injection of annexin A2-depleted cancer cells was severely impaired compared to tumours initiated with control cancer cells." (PMID 23434659, 2013). "The extensive tumor development and peritoneal metastasis observed with mouse IgG treatment was significantly reduced in mice treated with annexin A2 neutralizing antibody." (PMID 23945256, 2013). "We investigated the possible mechanisms for the reduced tumor burden in the annexin A2 antibody treatment group by analysing tumor cell proliferation, cell apoptosis and angiogenesis." (PMID 23945256, 2013). "Several reports have previously shown that upregulation of annexin A2 in tumours correlates with chemoresistance, but they were unable to explain the mechanism(s) by which this occurs." (PMID 23434659, 2013). "The tumours formed from annexin A2-depleted cancer cells also showed significantly enhanced protein oxidation (sensor for cellular oxidative damage) compared to tumours initiated with control cancer cells." (PMID 23434659, 2013). "Anti-annexin A2 antibodies have been also effective to inhibit tumor growth in a mouse model of LLC and reduce plasmin generation in vitro." (PMID 23519104, 2013). "Targeting annexin A2 with antibodies has been routinely used by researchers to reduce tumor progression and metastasis." (PMID 23519104, 2013). "Tumor growth of the annexin A2 depleted cells was rescued by application of the anti-oxidant N-acetyl cysteine (NAC)." (PMID 23519104, 2013). "We will further discuss the importance of annexin A2 redox regulatory function in disease, with a particular focus on tumour progression." (PMID 23434659, 2013). "ANXA2 protein in the tissue was expressed either at the cell membrane or in the cytoplasm of cirrhotic and tumor cells." (PMID 23946789, 2013). "Nevertheless, annexin A2 has been suggested to be capable of modulating key events in tumor progression mainly those involving invasion, metastasis, and drug resistance." (PMID 23519104, 2013). "Taken together, these results delineate an important role of annexin A2 in tumor growth by functioning as a redox-regulatory protein." (PMID 23519104, 2013). "Annexin A2 possibly provides chemoresistance to tumor cells by acting as an anti-oxidant and protects cellular components against oxidative damage." (PMID 23519104, 2013). "Increased extracellular levels of AnxA2 in tumours correlate with neoangiogenesis, metastasis and poor prognosis." (PMID 23555942, 2013). "They suggested that ANXA2 at the cell surface of tumor/endothelial cells provides for the mechanical assembly of plasminogen activator and plasminogen, which locally activates plasminogen to plasmin." (PMID 23950866, 2013). "In contrast, it is undetectable in normal and hyperplastic breast ductal epithelium suggesting a role of annexin A2 in malignancy and tumor invasiveness." (PMID 23519104, 2013). "Anxa2 is up-regulated in various tumor types and plays multiple roles in cellular functions, including tumorigenesis, proliferation, cell migration, invasion and adhesion." (PMID 23691485, 2012). "Accumulating evidence suggests that ANXA2 and its receptor axis plays an important role in the tumor microenvironment and metastasis, and it has been recognized as an attractive target for the development of anti-cancer/anti-metastatic agents." (PMID 22913272, 2012).
tumor (continued). "The AnxA2 knock-out mouse does, however, demonstrate defects in neoangiogenesis, a related process that provides tumours with the necessary blood flow for growth." (PMID 22505935, 2012). "We also used a previously established orthotopic model in which PDAs metastasizeto the peritoneum to confirm that ANXA2 can initiate metastasis from aprimary tumor in addition to facilitating the seeding of PDA metastases in theliver." (PMID 21572519, 2011). "This suggested that the oxidative stress that is known to occur during tumor growth, had a more severe effect on the ANXA2 depleted HT1080 cells than the control HT1080 cells." (PMID 22185818, 2011). "At the end point of the experiment the ANXA2 depleted HT1080 tumor volume was only 8% smaller than the HT1080 control tumors." (PMID 22185818, 2011). "We observed a significant impairment of tumor growth by ANXA2 depleted HT1080 and A549 cancer cells compared to control cells." (PMID 22185818, 2011). "Similar to themice receiving ANXA2 shRNA, mice in the ANXA2 antibody groupdied due to tumor progression at the splenic bed, suggesting this anti-ANXA2antibody therapy does not inhibit the growth of primary PDAs." (PMID 21572519, 2011). "We observed that in the presence of NAC tumor growth in animals injected with ANXA2-depleted cancer cells was identical to tumor growth in animals injected with control cancer cells." (PMID 22185818, 2011). "We alsoevaluated a panel of PDA tumor cell lines and 52 fresh tissue specimens and showedthe frequent expression of cell surface ANXA2 in primary PDAs, which furthersupports a role for ANXA2 in PDA progression." (PMID 21572519, 2011). "Annexin A2, a Ca2+-binding protein, has a function in promoting tumor cells invasion and metastasis through its interaction with matrix proteins." (PMID 19216771, 2009). "Advances in ANXA2-targeted therapies leverage its tumour-specific surface expression." (PMID 40234383, 2025). "ANXA2 not only inhibits tumour cell apoptosis but also suppresses T-cell immune functions." (PMID 40234383, 2025). "Notably, ANXA2 knockdown suppresses macrophage M2 polarization, suggesting its dual roles in orchestrating macrophage trafficking to tumour sites and promoting immunosuppressive M2 differentiation." (PMID 40234383, 2025). "Given the significant role of ANXA2 in inhibiting tumour cell apoptosis, we sought to explore whether and how this inhibition of apoptosis by ANXA2 affects tumour immunity." (PMID 40234383, 2025). "Additionally, we discuss the connection between this regulation of apoptosis and tumour immunity, as well as a potential role of ANXA2 in resistance to tumour cell therapy and its promise as a therapeutic target for cancer treatment." (PMID 40234383, 2025). "Therefore, this review elucidates the roles and mechanisms of ANXA2 in regulating apoptosis in tumour cells from the perspectives of ROS, autophagy, the DNA damage response, and glucose metabolism." (PMID 40234383, 2025). "For instance, ANXA2-enriched sEVs produced by culturing and engineering BMSCs from BALB/c nude mice with ANXA2-loaded lentiviral plasmids effectively suppressed the growth, invasion, and migration of PCa cells and reduced tumor growth in the mice by targeting M2 macrophages." (PMID 40114183, 2025). "Notably, the AP-9R aptamer can antagonize the expression of Annexin A2, thereby inhibiting tumor progression." (PMID 40948789, 2025). "When tumour cells experience stress responses such as nutrient stress induced by the microenvironment, ANXA2 activation and upregulation induce autophagy, promoting the degradation of intracellular components to provide energy and cope with starvation, which is reversible and protective autophagy." (PMID 40234383, 2025). "The interaction between ANXA2 and EZH2 in cellular senescence and pyroptosis merits further investigation, as ANXA2’s pro-inflammatory effects may influence tumor therapy responses." (PMID 40018411, 2025).
tumor (continued). "ANXA2 is also thought to play a crucial role in the occurrence and development of tumors, particularly in enhancing the invasiveness and metastatic capability of tumor cells." (PMID 40481236, 2025). "Elevated ANXA2 expression correlates with advanced clinical stage (III-IV), lymph node metastasis, and positive associations with HER2 and Ki67 levels, implicating its role in tumour proliferation and invasion." (PMID 40234383, 2025). "Therefore, a deep understanding of the regulatory mechanisms of ANXA2 in tumour cell apoptosis and its relationship with immune evasion can provide new targets for cancer therapy." (PMID 40234383, 2025). "In cellular senescence, ANXA2 mediates responses to DNA damage and may affect the transformation of tumor cells into a drug-resistant state by regulating the regenerative potential of senescent cells." (PMID 40018411, 2025). "Therefore, it can be inferred that tumour cells inhibit apoptosis through moderate autophagy activation by ANXA2." (PMID 40234383, 2025). "Additionally, we explored the relationships between tumour cell apoptosis mechanisms and cellular inflammation and immunity and how ANXA2 influences tumour cell inflammation and immunity through its antiapoptotic mechanisms." (PMID 40234383, 2025). "However, many unresolved questions remain regarding the role of ANXA2 in regulating tumour cell apoptosis and immune mechanisms." (PMID 40234383, 2025). "Interestingly, tumor-infiltrating M1-macrophages were also decreased in high-ANXA2 samples (P = 0.010)." (PMID 38519766, 2024). "The Vδ3 cells in the tumours were often oligoclonal with one or a few dominating clones, and they may recognize tumour neoantigens or stress signals in the tumour cells, such as Annexin A2." (PMID 38953978, 2024). "Furthermore, the expression level of ANXA2 in tumor cells affects the cytoskeletal composition and the plasminogen/plasmin system, playing a crucial role in tumor migration." (PMID 39350574, 2024). "Its phosphorylated form, p-ANXA2 (Tyr23), may promote tumor growth and metastasis through the MYC-HIF-1α-VEGF signaling axis." (PMID 39594718, 2024). "Since the oncogenic role of the NF-kB signaling pathway is well documented, it is biologically plausible to infer that HAR1A may exert tumor-suppressing functions by repressing the ANXA2/NF-kB axis." (PMID 38688909, 2024). "It has been hypothesized that ANXA2 is overexpressed in a number of human malignancies and has a major effect on the adhesion, proliferation, apoptosis, invasion, and metastasis of tumor cells." (PMID 38711550, 2024). "ANXA2 has also been demonstrated to be involved in tumor angiogenesis and metastasis." (PMID 38519766, 2024). "In summary, we demonstrated that NASP promotes tumor progression and radioresistance and provides a plausible molecular mechanism involving ANXA2 phosphorylation and nuclear translocation, as well as enhanced STAT3 signaling, which promotes radioresistance and enhances tumorigenic behavior." (PMID 38605477, 2024). "This interaction between annexin A2 and actin may inhibit the progression and migration of tumor cells." (PMID 38931461, 2024). "Moreover, abnormal ANXA2 expression in cancer cells has profoundly impacted tumor angiogenesis, tumor cell proliferation, apoptosis, adhesion, invasion, and metastasis." (PMID 38658569, 2024). "We intended to explore the function of ANXA2 in tumor microenvironment of RCC." (PMID 38519766, 2024). "These growing evidences showed the important role of ANXA2 in tumor immune escape." (PMID 38519766, 2024). "Annexin A2 (AnxA2) is ubiquitously expressed and presents an abundance typically in endothelial cells and monocytes, and the upregulation of AnxA2 expression is observed in tumor cells and regarded as a marker of multiple tumors." (PMID 38495790, 2024). "The results also supported further investigations of ANXA2’s function in tumor immunity." (PMID 38519766, 2024).
tumor (continued). "Additionally, scatter plots revealed a positive correlation between TREM2 and ANXA2 with both the StromalScore and ImmuneScore, suggesting their roles in modulating the tumor microenvironment." (PMID 39697329, 2024). "The nomograms further showed the good prognostic value of ANXA2 in different tumor types." (PMID 36713082, 2023). "Similarly, FITC‐YW7 showed greater binding on ANXA2 high expressed PAAD tumor than paired normal adjacent pancreas tissues." (PMID 36453020, 2023). "Thus, we further explored the binding selectivity of YW7, based on the abnormal expression of ANXA2 in tumor cells." (PMID 36453020, 2023). "ANXA2 is a widely studied member of the annexin superfamily and is expressed in various cell types, including dendritic cells, monocytes, macrophages, bone marrow cells, epithelial cells, endothelial cells, neurons and tumor cells." (PMID 36713082, 2023). "Thus, we further checked TCR sharing between GZMK+ TEM and TEX/ANXA2+ TEM across different tissues and found that TEX and ANXA2+ TEM cells in tumor sites shared more TCR clones with ascites-derived GZMK+ TEM cells than tumor-derived GZMK+ TEM cells." (PMID 37488416, 2023). "Additionally, Annexin A2 protein expression has manifested a favourable connection with the aggressiveness of tumours, resistance to anti-cancer drugs, shorter disease-free survival, and worse overall survival in clinical studies." (PMID 37482693, 2023). "Additionally, Annexin A2 is involved in mycoplasma-induced the pathogenicity of mycoplasma, tumour metastasis, and tumour drug resistance." (PMID 37482693, 2023). "ANXA2 was verified to be one of the key candidate genes in the process of tumor invasiveness." (PMID 36750863, 2023). "Our data demonstrated the prominent tumor selectivity of ANXA2‐targeted fluorescent probes." (PMID 36453020, 2023). "Once ANXA2 binds to fibrinogen and tissue-type fibrinogen activators, it can activate metalloproteinase (MMPs), which will in turn disrupt the integrity of the extracellular matrix, resulting in tumour invasion and metastasis." (PMID 36936694, 2023). "In tumours, ANXA2 is able to promote tumour cell migration and neovascularization." (PMID 36932468, 2023). "In conclusion, we demonstrated the differential expression of ANXA2 between tumor and normal tissues, and ANXA2 could be used as a prognostic biomarker for various tumors." (PMID 36713082, 2023). "ANXA2 was upregulated in cluster 10 ECs, and is involved in increasing the permeability between ECs by reducing the expression of inter-endothelial binding proteins, which is conducive to tumor metastasis." (PMID 37533434, 2023). "Annexin A2 is widely used as a marker for a variety of tumours." (PMID 37753171, 2023). "Also, sEV annexin A2 in serum was shown to have a prognostic value with a positive correlation to tumour grade of TNBC and poor survival." (PMID 36797736, 2023). "In summary, Anxa2 is involved in not only cell-surface fibrinolysis but also various cellular functions, including the inflammatory response, injury signaling, wound healing, and tumor progression, thus indicating its involvement in various human pathologies." (PMID 37955107, 2023). "Through the use of suppression subtractive hybridization and other techniques, they identified Annexin A2 as a candidate gene that may be related to tumour growth inhibition in the 180-850 bp sequence." (PMID 37482693, 2023). "ANXA2 has been reported to promote tumor proliferation and metastasis as well as AKT activation." (PMID 36806050, 2023). "Aberrant expression of ANXA2 is observed in a variety of malignancies, including hepatocellular carcinoma, and plays a key role in tumor formation and progression by regulating cell proliferation, apoptosis, adhesion, invasion, metastasis, and tumor neovascularization." (PMID 38082327, 2023). "In addition to ANXA1, the ANXA proteins ANXA2, ANXA9 and ANXA10 are associated with tumour cell adhesion, invasion and metastasis." (PMID 36936694, 2023).
tumor (continued). "Previous evidence indicated that miR155HG was overexpressed and acts as a tumor suppressor to upregulate ANXA2 forming a loop that could promote the GBM's malignant progression." (PMID 35874629, 2022). "Furthermore, the expression level of AnxA2 alone was able to distinguish the tumor from normal tissue, with an area under the curve (AUC) of 0.6346 ± 0.0576 (95% CI 0.5217–0.7475, p = 0.0472)." (PMID 36428758, 2022). "Some other studies had also suggested that ANXA2 could increase the activity of DNA polymerase and thus promote the invasive growth and metastasis of tumor cells to surrounding tissues." (PMID 35211410, 2022). "The M-IHC panel included CD68/CD163 (macrophage cocktail) and CK to determine whether ANXA2 staining was predominantly localized to tumor cells or macrophages." (PMID 36377658, 2022). "Hence, we intend to use the combined sEV-derived AnxA2 protein and mRNA biomarker to predict the patient tumor stages, grades, and to study the best suitable drug for the early treatment in TNBC patients." (PMID 36612209, 2022). "The high expression of AnxA2 was accompanied by high tumor stage and grade." (PMID 36428758, 2022). "Similarly, our limited studies suggest that ANXA2 is largely elaborated from the tumor cell compartment, though minor contributions from other cellular sources remain a possibility." (PMID 36377658, 2022). "Previous studies on the ANXA2 mechanism mainly focused on tumor diseases." (PMID 35991124, 2022). "Conversely, there are tumors where ANXA2 acts as a tumor suppressor." (PMID 36247003, 2022). "While the human Ahnak gene was initially cloned from tumor cells and later characterized as a tumor suppressor, chemotherapy-induced p11/AnxA2/Supt6h complex is known to facilitate Oct4-mediated gene transcription and thereby is involved in chemotherapy-induced breast cancer stem cell enrichment." (PMID 36046712, 2022). "However, PF-562271 treatment and ANXA2 silencing both partially suppressed the promotion of tumor growth by LINC00941 overexpression." (PMID 35977942, 2022). "Tumor-derived ANXA2 drives Arg1 gene expression in neutrophils." (PMID 36377658, 2022). "Annexin II (AnxA2, A2) is a Ca2+-dependent, anionic phospholipid-binding protein that belongs to the ubiquitous multigene annexin family, expressed on most of the endothelial cells, mononuclear macrophage, marrow cells, and some tumor cells." (PMID 35328533, 2022). "After CLG-ANXA2 was taken up by tumor cells, shANXA2 reduced ANXA2 mRNA and protein levels." (PMID 36247003, 2022). "The inhibition of ANXA2 also inhibits tumor cell growth, metastasis, and survival." (PMID 36589842, 2022). "Furthermore, xenografts of PC-3 cells expressing miR-936 in male BALB/c nude mice significantly reduced ANXA2 expression as well as subcutaneous tumor formation in vivo, indicating a tumor suppressor role of miR-936 in PCa." (PMID 36224238, 2022). "Bind to tumor suppressor miR-342-3p, enhance the ANXA2 expression, promote cancer development." (PMID 35359397, 2022). "Moreover, this potential tumor suppressor miR-936 regulates the ANXA2 mRNA expression by binding to its coding and 3’UTR regions." (PMID 36224238, 2022). "This makes ANXA2 a potential candidate target for tumor immunotherapy in the future." (PMID 34675316, 2021). "The targeting peptide bind to ANXA2 on tumor cells and trigger the endocytosis, endosomes take the composition into cytoplasm and release the cytotoxic agent from the composition and exert cytotoxicity such as interrupting mitochondria, blocking cell division, damaging DNA." (PMID 33995636, 2021). "Reduced form of ANXA2 can protect tumor proteins from oxidation." (PMID 33995636, 2021). "Interestingly, the anti-tumor cytokine IFNγ-expression by T cells was significantly enhanced through the combination of anti-PD-1 antibody with Lm-ANXA2 vaccine therapy." (PMID 34638560, 2021).